KRAS (KRas proto-oncogene, GTPase)
Diseases named in the same sentence as KRAS in open-access papers (continued):
Sharing a sentence is not in itself a finding about the gene and the disease.
pancreatic cancer (continued). "Oncogenic KRAS mutations are observed in more than 90% of pancreatic cancer patients; among those, the KRASG12D mutation is the most common and present in nearly 40% of pancreatic cancer patients." (PMID 37958351, 2023). "In addition to mutant KRAS, other growth factors have been shown to stimulate growth of human pancreatic cancer, including gastrin." (PMID 36614194, 2023). "Furthermore, the NCCN guidelines also recommended somatic testing of KRAS, BRAF, HER2, PALB2, MMR deficiency, and oncogenic gene fusions for pancreatic cancer patients with advanced or metastatic diseases." (PMID 36999792, 2023). "Also, it was reported that a subset of human pancreatic carcinomas showed copy number gains of PTHrP (encoded by PTHLH gene), as part of KRAS amplification, which is frequent in pancreatic carcinomas." (PMID 37540958, 2023). "We further identified and described a G4mid-selective small molecule, NSC 317605, and demonstrated the synergistic activities with enhanced selectivity for the KRAS promoter G4mid, improved transcriptional downregulation and correlating effects on KRAS-dependent AsPc-1 pancreatic cancer cells." (PMID 35216221, 2022). "The reason for exploring KRAS mutation status as a prognostic biomarker rather than any other potentially useful biomarkers, such as Ki67, is that these patients were being screened for potential inclusion in a clinical study of EGFR inhibition in KRAS wild-type pancreatic cancer." (PMID 36231137, 2022). "However, Mirati Therapeutics showed partial responses in 5 patients and a disease control rate of 100% in 10 KRAS G12C mutant pancreatic cancer patients." (PMID 36048281, 2022). "By contrast, a protein-rich diet showed little effects on oncogenic KRAS-mediated pancreatic neoplasm, suggesting that consuming a protein-rich diet could be a more viable dietary intervention approach for pancreatic cancer patients." (PMID 35681705, 2022). "KRAS mutant cancer cells, being the progenitor of most pancreatic cancers 27, are defined by radical metabolic transformations to survive the hostile microenvironment, and treating them by exploiting such features has emerged as a fresh perspective that is worth trying." (PMID 35154474, 2022). "ERK Phosphorylation induced by mutated KRAS overactivates the RAS-MAPK signaling pathway, which may significantly contribute to pancreatic cancer progression." (PMID 35433491, 2022). "KRAS drives tumor growth in pancreatic cancer by activating PyM." (PMID 35224098, 2022). "MIA PaCa-2, a human pancreatic cancer cell line with a homozygous KRASG12C allele, displayed appreciably higher macropinocytosis levels as measured by 70 kDa dextran uptake compared to another pancreatic cell line with wild-type KRAS (i.e. BxPC-3) 16,25." (PMID 35154489, 2022). "Exosomal KRAS status could predict disease progression with sensitivity and specificity of 75.4% and 92.6% respectively, with a positive exosomal KRAS result indicating an 8.17 times greater probability of having localized pancreatic cancer." (PMID 35454933, 2022). "Therefore, KRAS protein trafficking can be successfully inhibited by statin treatment in pancreatic cancer." (PMID 35409064, 2022). "All these results suggest that the KRAS–JNK axis could be a potential target in CSC/CSLC-directed therapies against pancreatic cancer." (PMID 36232313, 2022).
pancreatic cancer (continued). "The question that whether co-targeting KRAS and IL-33 increases the probability of pancreatic cancer prevention arises and remains to be validated." (PMID 36224645, 2022). "Interestingly, we demonstrated that primary pancreatic cancer cells display high OXPHOS heterogeneity, which was unrelated to KRAS mutations." (PMID 35159234, 2022). "It is especially remarkable that significant and specific knockdown of the KRAS G12D allele, with no influence on the wild-type allele, in pancreatic cancer cells was accomplished and inhibited tumor growth in vitro and in xenograft mouse models." (PMID 35014625, 2022). "Interestingly, treatment with exosomes carrying shRNA to target KRAS has suppressed tumor progression and enhanced survival in pancreatic cancer mouse models." (PMID 35328535, 2022). "Thus, KRAS contributes to the unregulated growth of pancreatic cancer cells, and directly targeting metabolic pathways as a therapeutic target is a major challenge." (PMID 36408139, 2022). "For example, KRAS signaling had been reported to be predictive of response to immunotherapy in colon tumor and could construct an immunosuppressive environment in pancreatic cancer." (PMID 35664743, 2022). "The authors concluded that measurement of KRAS ctDNA could be used to predict disease recurrence in pancreatic cancer patients." (PMID 36579573, 2022). "Overexpression of CXCL16 can promote KRAS-induced pancreatic tumor growth." (PMID 35957897, 2022). "Modulating oncogenic KRAS expression in pancreatic cancer cells demonstrated distinct rewiring of central carbon metabolism to shift glycolytic intermediates into bioenergetic pathways and a preferential use of glutamine for tricarboxylic acid (TCA) cycle metabolism." (PMID 36411320, 2022). "In addition, high 1CM activity has been linked to increased tumor aggressiveness and reduced prognosis in several cancer entities, and a dependency of MTHFD2 on KRAS and its prognostic impact was described in AC, colorectal, and pancreatic cancer." (PMID 35888776, 2022). "Drugs against other classically nontargetable mutations such as KRAS G12D, present in 40% of pancreatic cancer cases, are currently under investigation." (PMID 35580504, 2022). "KRAS promotes the gene expression of GSKβ in pancreatic cancer." (PMID 34978469, 2022). "Thus, clarifying the precise molecular mechanism of KRAS in the development of pancreatic cancer is a pivotal way to conquer it, and the inhibition of KRAS downstream targets is considered an effective strategy." (PMID 36017891, 2022). "We examined the dose-dependent effects of KRAS-targeting PPRHs (144 h) on the viability of KRAS mutant expression pancreatic cancer cell lines AsPc-1 (G12D, highly addicted to KRAS) and MiaPaCa-2 (G12C, moderately addicted to KRAS) and KRAS overexpressing ovarian cancer SKOV-3 cell lines." (PMID 35216221, 2022).
pancreatic cancer (continued). "Recently, pancreatic cancer has been shown to undergo reprogramming in lipid-related and acetyl-CoA metabolism pathways, extending our finding about the importance of acetyl-CoA metabolism in romidepsin sensitivity in KRAS-activated cell lines." (PMID 35681624, 2022). "We monitored the dynamic changes in one pancreatic cancer patients (PanC03) during treatment by aligning the total copies of KRAS transcripts (obtained by following the modified workflow) and serum CA19‐9 levels (U mL−1) with CT images taken before and post‐treatment." (PMID 35486030, 2022). "As expected, KRAS was overexpressed in pancreatic cancer compared with non-tumor and KRAS expression caused a worse clinical outcome in pancreatic cancer." (PMID 35785187, 2022). "Thus, the development of pan-KRAS inhibitors is being pursued extensively for pancreatic cancer therapy due to drug resistance." (PMID 36291766, 2022). "Previous reports have shown that the injection of exosomes carrying KRAS siRNA could impede tumor growth and metastasis in pancreatic cancer mouse models." (PMID 35328535, 2022). "In this study, we investigated whether gossypol activates the apoptosis-mediated ER stress pathway in two pancreatic cancer cell lines, BxPC-3 cells containing wild-type Kirsten Ras proto-oncogene (KRAS), and MIA PaCa-2 cells containing mutant KRAS [43, -45]." (PMID 35283426, 2022). "Moreover, KRAS, the most frequently mutated RAS isoform, happens not only in pancreatic cancer but also in lung cancer, multiple myeloma, and colorectal cancer." (PMID 36263162, 2022). "Early-stage pancreatic cancer driven by mutant KRAS has been shown to increase plasma BCAA levels." (PMID 36408139, 2022). "Therefore, to improve the poor overall survival rate of pancreatic cancer patients, it is urgent to explore the downstream effector molecules of KRAS." (PMID 36017891, 2022). "Given only some patients benefit from MEK inhibitors in the treatment of KRAS-mutant pancreatic cancers, we were encouraged to investigate whether different KRAS-mutant human pancreatic cancer cell lines respond differently to MEK inhibition." (PMID 35806187, 2022). "Furthermore, an ongoing phase I clinical trial in KRAS G12D-mutant pancreatic cancer is evaluating the optimal dose and adverse effects of STEX loaded with KRAS G12D siRNA (NCT03608631)." (PMID 36591444, 2022). "However, no large sample size studies have performed survival analysis on patients with resectable pancreatic cancer with different KRAS subtypes." (PMID 36582783, 2022). "The work described herein identifies and combines two therapeutic strategies–PPRHs and the small molecule NSC 317605–capable of stabilizing the KRAS promoter G4mid structure, decreasing transcription and synergistically modulating KRAS addicted AsPc-1 pancreatic cancer cells." (PMID 35216221, 2022). "Treatment with LODER-encapsulated anti-KRASG12D siRNA (siG12D LODER) inhibits cancer cell proliferation and epithelial-mesenchymal transition with significant decrease in KRAS levels and inhibits orthotopic pancreatic tumor growth and prolonged mouse survival in vivo." (PMID 35057033, 2022). "YAP1 expression levels are associated with poor patient outcome and the squamous subtype in PDAC, with YAP acting to bypass KRAS dependency in pancreatic cancer cell lines, suggesting an ability to induce transcription of targets up-regulated on aberrant KRAS signalling." (PMID 35119068, 2022). "We determined the effect of KRAS status on the proliferation rate and cell cycle profile of these cells, and, finally, examined which DNA repair mechanism predominates in the analyzed pancreatic cancer cells." (PMID 36077614, 2022).
pancreatic cancer (continued). "A549 NSCLC and MiaPaCa-2 pancreatic cancer cells expressing significant KRAS-driven NQO1 levels were hyper-sensitive to treatment with the PARPi rucaparib + KP372-1, but this sensitivity disappeared when the cancer cells were treated with the NQO1 inhibitor DIC." (PMID 36203459, 2022). "Our data indicated that GILncSig is able to identify a sub-population of pancreatic cancer patients who might be at a higher mortality rate and thus deserve a more radical treatment regimen that could otherwise go unnoticed due to their KRAS wild type status." (PMID 36148233, 2022). "Although the methods and experimental conditions are different, the trends are similar: MIA PaCa-2, which is a human pancreatic cell line with mutant KRAS, demonstrated obviously elevated macropinocytosis compared to the KRAS wt pancreatic cancer cell line BxPC-3." (PMID 35154489, 2022). "Targeting KRAS downstream signaling remains an important therapeutic approach in pancreatic cancer." (PMID 36534167, 2022). "G13 mutations are also seen in about 18% of all KRAS mutations in colon cancers but are almost never seen in lung and pancreatic cancers." (PMID 36284306, 2022). "Changes in transcription tied to cytotoxicity were also examined in Panc1 pancreatic cancer cells, wherein trends indicating a decrease in KRAS with compounds NSC and 9a were also observed (vehicle normalized expression was noted to be 0.57 ± 0.36 and 0.55 ± 0.34), but significance was not noted." (PMID 36011352, 2022). "We recently showed that the acyl-coA synthetase long chain 3 (ACSL3), an enzyme that promotes the activation and retention of extracellular unsaturated FAs by converting them into hydrophilic fatty acyl-CoA esters that cannot exit cells, is overexpressed in KRAS-driven lung and pancreatic cancer." (PMID 34998392, 2022). "A cooperative effect of KRAS mutation and the expression of c-MYC for invasion, as also observed in HCC44 cells in our model, and for immune modulation has been shown previously in animal studies for lung and pancreatic cancer." (PMID 35565305, 2022). "Notably, we observed similar results in KRAS mutant lung and pancreatic cancer cells, implying that GRB7 plays a critical role in RAS-driven cancer cells in the presence of MEKi." (PMID 34718347, 2022). "Therefore, at first, the effect of siRNA targeting KRAS (siKRAS) was examined in two different pancreatic cancer-derived cell lines, AsPC-1 and BxPC-3." (PMID 35804932, 2022). "Our previous study analyzed KRAS murine peptides for their implications in pancreatic cancer." (PMID 36298543, 2022). "KRAS mutations are observed in 94% and BRCA2 mutations in 6% of patients with pancreatic cancer." (PMID 35666369, 2022). "Notably, KRAS has been identified as the mediator of pro-proliferative effects of LINC01420 in pancreatic cancer." (PMID 35139853, 2022). "Whether KRAS expression was correlated with prognosis in pancreatic cancer patients, the TCGA-PAAD cohort was chosen to evaluate the impact of KRAS expression on survival rates." (PMID 34255132, 2022). "Although the specific mechanism of cell death induction of pancreatic cells remains to be analysed, from these biological studies, we can conclude that treatment with the peptidomimetic P1.3 kills pancreatic tumour cells expressing oncogenic KRAS, with a negligible effect in normal cells." (PMID 36138080, 2022). "This approach allowed us to obtain, in a quick and cost-effective manner, one compound (named here P1.3) that has the capacity to efficiently inhibit the interaction of RAS with its effectors in cells in vitro and inhibits survival of pancreatic tumour cells expressing oncogenic KRAS." (PMID 36138080, 2022). "For the present study we employed the pancreatic cancer cell lines MIA PaCa-2, frequently used to study KRAS G12C biology, AsPC1 a KRAS G12D mutated cell line and the tumorigenic BxPC-3 cells that shows epithelial morphology and moderate differentiation, but is unique in lacking a KRAS mutation." (PMID 36048281, 2022).
pancreatic cancer (continued). "Additionally, pancreatic cancer cells release KRAS-G12D via exosomes during ferroptosis, and macrophages then take up these KRAS-G12D and undergo M2 polarization mediated by AGER to promote tumor progression." (PMID 35444656, 2022). "This cell line is poorly representative of the human disease since it does not carry a KRAS mutation which is present in >90% of human pancreatic cancers." (PMID 35454943, 2022). "Here, we outline emerging direct targeting and immunotherapeutic strategies, highlight results of corresponding preclinical and clinical trials in the context of lung, colorectal, and pancreatic cancer, and focus on clinical applications targeting oncogenic KRAS proteins." (PMID 35014625, 2022). "In addition, downregulation of NUTF2P3-001 inhibits the viability, proliferation, and invasion of pancreatic cancer cells and contributes to a decrease in KRAS expression." (PMID 34489556, 2022). "It is the first report to focus on the possibility that MYEOV may act as a ceRNA to form an interaction network with some pancreatic cancer-related genes such as KRAS and serve as a strategic therapeutic target of pancreatic cancer treatment." (PMID 36358856, 2022). "KRAS plays a vital role in developing PDAC-type pancreatic cancer." (PMID 35409064, 2022). "In addition, KRAS wild-type pancreatic cancer and the detailed regulatory molecular mechanism of different cell death modes induced by combined therapy should be explored and confirmed in the future." (PMID 35468095, 2022). "KRAS is not so frequently mutated in endometrial cancer as in pancreatic cancer but, still, KRAS mutations are present in 10–30% of type I estrogen-related endometrial cancer." (PMID 36497428, 2022). "Thus, KRAS maintains the stemness of pancreatic cancer cells through a unique Lin28B/let-7i/TET3 feedback loop." (PMID 35651786, 2022). "KRAS is a classic oncogene that is actively involved in the pathogenesis of pancreatic cancer." (PMID 36148233, 2022). "For instance, KRAS signaling is a critical driver in pancreatic cancer." (PMID 36419844, 2022). "Although KRAS activation was linked to SRC overexpression in pancreatic carcinoma, the same study failed to establish a link between mt KRAS and SRC overexpression." (PMID 35877239, 2022). "Pancreatic tumors with KRAS actionable alterations were mainly driven by G12 codon alterations." (PMID 33889297, 2021). "The presence and/or absence of a KRAS nonreference allele (i.e., potential variant or mutation) in ccfDNA did not discriminate between pancreatic tumor patients (i.e., cases) and controls in the individual replicates." (PMID 34298235, 2021). "An estimated 90% of patients with pancreatic cancer have mutant KRAS specific to tumor cells." (PMID 34771675, 2021).